MYC (MYC proto-oncogene, bHLH transcription factor)
Diseases named in the same sentence as MYC in open-access papers (continued):
Sharing a sentence is not in itself a finding about the gene and the disease.
hypertrophic cardiomyopathy (5 papers, 2018 to 2023). A condition in which the myocardium is hypertrophied without an obvious cause. "We first noted that patients with hypertrophic cardiomyopathy had lower MYC levels than the control group in GSE141910." (PMID 37498303, 2023). "Previous reports have suggested that inhibition of MYC is a potential therapeutic approach for treating hypertrophic cardiomyopathy." (PMID 37234159, 2023). "Inhibition of MYC was a potential therapeutic approach in the treatment of hypertrophic cardiomyopathy." (PMID 32460775, 2020). "Previous report suggests that inhibition of MYC is a potential therapeutic approach in the treatment of hypertrophic cardiomyopathy." (PMID 32460775, 2020).
Hypoglycemia (5 papers, 2018 to 2023). A decreased concentration of glucose in the blood. "The process would include variable periods of hyperinsulinemia with the consequent systemic MYC activation of glycolysis, glutaminolysis, structural lipidogenesis and further exacerbation of hypoglycemia, the result of MYC's known role as an inhibitor of liver gluconeogenesis." (PMID 30167086, 2018). "Interestingly, under these same high glucose conditions, antimycin A treatment also fails to increase the mRNA half-lives of VEGF, MYC and CYR61 suggesting that induction of mtROS can substitute for hypoxia but not hypoglycemia." (PMID 30305827, 2018).
insulinoma (5 papers, 2016 to 2025). "Finally, we highlight that previously reported mitogenic targets of the harmine class of beta cell mitogenic drugs—DYRK1A (from the red module), and MYC (also upregulated in insulinomas) and its inhibitor, MNT —are also present in this analysis." (PMID 28974674, 2017).
malignant pleural mesothelioma (5 papers, 2014 to 2019). A malignant neoplasm that arises from mesothelial cells in the pleura and shows a diffuse growth pattern. "In this regard, frequent coamplification and cooperation between c-MYC and PVT1 oncogenes have been observed to promote malignant pleural mesothelioma." (PMID 29701689, 2018).
osteoarthritis (5 papers, 2022 to 2023). A noninflammatory degenerative joint disease occurring chiefly in older persons, characterized by degeneration of the articular cartilage, hypertrophy of bone at the margins and changes in the synovial membrane. "Four genes, MYC, JUN, DUSP1 and NFKBIA, were selected as potential diagnostic biomarkers in osteoarthritis." (PMID 36681837, 2023). "The degree of articular chondrocyte apoptosis in osteoarthritis is positively correlated with the degree of cartilage degeneration, and MYC participates in the process of chondrocyte apoptosis." (PMID 37551168, 2022). "Consistently, we found that expression of MYC, JUN and DUSP1 was markedly reduced in synovial tissues of osteoarthritis patients than that of normal controls (p value < 0.05)." (PMID 36681837, 2023). "Among them, four genes (MYC, JUN, DUSP1 and NFKBIA) specifically expressed in immune system were identified and clinical samples revealed consistent change of these four genes in synovial tissue retrieved from patients with osteoarthritis." (PMID 36681837, 2023). "Finally, four feature genes, including MYC, JUN, DUSP1 and NFKBIA were identified, which had well predictive performance in osteoarthritis." (PMID 36681837, 2023). "MYC, JUN, DUSP1 and NFKBIA might be biomarkers and potential therapeutic targets in osteoarthritis." (PMID 36681837, 2023).
ovarian serous cystadenocarcinoma (5 papers, 2018 to 2023). A malignant serous cystic epithelial neoplasm arising from the ovary. "MYC mRNA expression correlated with expression of CX3CR1 in specimens of serous ovarian cystadenocarcinoma." (PMID 29712888, 2018).
plasma cell leukemia (5 papers, 2020 to 2025). An aggressive plasma cell neoplasm characterized by the presence of neoplastic plasma cells in the peripheral blood. "A similar case report demonstrated double-hit plasma cell leukemia patient with IGH/MYC and IGH/BCL2 translocations." (PMID 32249811, 2020). "A comparable case study presented a patient with double‐hit plasma cell leukemia characterized by IgH/BCL2 and IgH/MYC translocations." (PMID 40859868, 2025). "Indeed, MYC is overexpressed during MM progression, with increases in expression, as observed during MGUS to MM transition, and with the highest levels of expression in plasma cell leukemia (PCL)." (PMID 34503175, 2021).
renal cysts (5 papers, 2013 to 2023). A fluid filled sac in the kidney. "Elevated MYC appears to be a signature of renal cystic disease and may define a causative pathway." (PMID 38125876, 2023). "In addition, MYC increases the expression of inflammatory and fibrotic factors, which may significantly contribute to the pathogenesis of cystic kidney diseases." (PMID 38125876, 2023).
sebaceous carcinoma (5 papers, 2013 to 2025). "We next examined the expression of MYC protein in all sebaceous carcinomas that were subject to NGS, as well as four additional OA tumors, using immunohistochemistry." (PMID 34445161, 2021). "We have demonstrated equivocal copy gains of MYC in 54% and low-level gains suggestive of amplification in 18% of sebaceous carcinomas, with the latter confirmed by FISH." (PMID 34445161, 2021). "MYC protein expression, as assessed by immunohistochemistry, was present in almost all sebaceous carcinoma cases." (PMID 34445161, 2021). "For this reason, high-MYC-expressing neoplastic cells, including three recently established primary sebaceous carcinoma cell lines, have demonstrated sensitivity to glutamine analogs following the selective suppression of the metabolic reactions that utilize glutamine." (PMID 40422212, 2025). "Similar to previous studies, immunohistochemical analysis of sebaceous carcinomas demonstrated increased MYC labeling of nuclei within intraepithelial and subepithelial tumor cells compared to absent to weak labeling of adjacent normal basilar epidermal, conjunctival, and sebaceous cells." (PMID 34445161, 2021). "Additionally, overexpressed MYC targets of miRNAs have been reported in sebaceous carcinomas with pagetoid features." (PMID 34445161, 2021). "Notably, most sebaceous carcinoma cases affecting the ocular adnexa exhibit MYC protein expression." (PMID 39421442, 2024).
Thrombocytopenia (5 papers, 2019 to 2025). A reduction in the number of circulating thrombocytes. "MYC exhibited strong associations with blood coagulation disorders, thrombotic microangiopathies, and thrombophilia, while NTAN1 was enriched in hematologic pathologies such as thrombocytopenia and hemolytic anemia." (PMID 41210882, 2025). "DDR inhibitors often share haematologic toxicities (anemia, neutropenia, thrombocytopenia), which may be exacerbated in combination with each other or with indirect MYC-targeting therapies (such as BETi)." (PMID 41561634, 2025).
thymic lymphoma (5 papers, 2013 to 2025). "In contrast, in thymic lymphomas, γH2AX and MYC levels showed weaker correlation and much greater variability for both genotypes." (PMID 40970130, 2025).
uterine cancer (5 papers, 2016 to 2024). Primary or metastatic malignant neoplasm involving the uterine corpus and/or the cervix. "Our analysis of gene expression profiles of uterine carcinomas with SUPT5H amplifications suggested that these amplifications enable such tumors to escape MYC-dependent transcriptional repression." (PMID 30928206, 2019). "Both MYC and ERBB2 have likewise shown associations with uterine cancers in earlier studies." (PMID 29716549, 2018).
uterine serous carcinoma (5 papers, 2015 to 2024). "For example, we propose that dysregulation of the critical master regulator MYC in uterine serous carcinomas may lead to treatment resistance." (PMID 26170901, 2015).
acne (4 papers, 2017 to 2025). An inflammatory process of the sebaceous glands which is characterized by comedones, nodules, papules and/or pustules on the skin. "Although it was originally a topical treatment of acne vulgaris, we found that it strongly bound to the c-MYC bHLHZip domain at the same binding pocket as the known inhibitor 10074-G5." (PMID 37627164, 2023). "It is thus relevant to explore whether these hub genes, like c-MYC, emerges as a pivotal regulatory hub not only in systemic cancers but also in cutaneous biology to influence sebaceous gland cell or keratinocyte differentiation and proliferation and contribute to acne." (PMID 40625748, 2025). "Some target genes were likely involved in acne development, including AR, IGF1/IGF1R, mTOR, GATA6, Wnt, IL6, FOXO1, PIK3, MYC." (PMID 40625748, 2025).
adenovirus infection (4 papers, 2015 to 2023). "This study demonstrates that MYC-dependent rewiring of host cell glutamine metabolism during adenovirus infection promotes virus replication." (PMID 26561297, 2015). "Together, our data support MYC activation-dependent regulation of glutamine metabolism during adenovirus infection through repression of miR-23 leading to upregulation of GLS, as well as MYC-dependent upregulation of the glutamine transporters, ASCT2 and LAT1." (PMID 26561297, 2015). "Another metabolic pathway found to be altered in a MYC activation-dependent manner during adenovirus infection is the hexosamine biosynthesis pathway." (PMID 26561297, 2015). "The increased labelling of proline from glutamine suggests MYC-induced stimulation of the proline biosynthesis pathway during adenovirus infection." (PMID 26561297, 2015).
adult T-cell leukemia (4 papers, 2020 to 2025). "In adult T-cell leukemia/lymphoma (ATLL) cell lines, the mRNA and protein level of c-MYC is higher than normal due to the aberrations of FBXW7 expression, which is correlated with ATLL proliferation and poor prognosis of patients." (PMID 35515121, 2022).
alcoholic liver diseases (4 papers, 2015 to 2025). A disorder caused by damage to the liver parenchyma due to alcohol consumption. "In addition to cancer, MYC was also reported to be involved in the regulation of metabolic diseases, including alcoholic liver disease and NAFLD." (PMID 36120320, 2022).
bladder urothelial carcinoma (4 papers, 2015 to 2025). "Then it focuses on FGFR3 and MYC dysregulation in urothelial bladder cancer pathogenesis as well as on the potential therapeutic implications." (PMID 39031286, 2024). "This review will summarize the current general understanding of FGFR signaling and MYC alterations in cancer, and the role of FGFR3 and MYC dysregulation in the pathogenesis of urothelial bladder cancer with the possible therapeutic implications." (PMID 39031286, 2024).
cervical tumors (4 papers, 2007 to 2024). "This allele‐specific activity can be extrapolated to the cervical tumour samples as well, because TAD3189 is the most recurrently integrated TAD among cervical tumours, and we also observed the overexpression of oncogenes MYC and PVT1 within them." (PMID 38013620, 2024). "ZNF382 was firstly identified as a direct repressor for several oncogenes (i.e., MYC, MITF, HMGA2, and CDK6) across distinct types of cancers, including lung, esophageal, colon, stomach, breast, and cervical tumors." (PMID 34638319, 2021). "Unlike in other cancers, however, we did not observe a concurrent increase in MYC mRNA levels in cervical tumors." (PMID 27232880, 2016).
cholestasis (4 papers, 2015 to 2021). Impairment of the bile flow caused by obstruction within the liver, or outside the liver in the bile duct system. "First, the researches unveiled a novel switch from MNT to c-MYC expression during cholestasis in vivo after bile duct ligation (BDL)—an experimental model of obstructive cholestasis—as well as after treatment of hepatocytes with a toxic bile acid." (PMID 28422055, 2017). "Interestingly, c-MYC expression was induced early and persisted until the end-point in a combined model of cholestasis and diethylnitrosamine (DEN)-induced carcinogenesis." (PMID 28422055, 2017). "In a mouse model of chronic cholestasis, developed to study the mechanisms by which cholestasis contributes to biliary carcinogenesis, MYC was upregulated during CCA progression and resulted in induction of cyclin D1, a protein that contributes to dedifferentiation and cell proliferation in CCA." (PMID 27127503, 2016). "In cholestasis and cholangiocarcinoma cells, MATα-1-MNT interaction drops, and there is a switch towards MYC and MAF protein complexes." (PMID 34572909, 2021).
cholesteatoma (4 papers, 2014 to 2023). A pathologic process characterized by the proliferation of keratinizing squamous epithelium resulting in the accumulation of keratin and cells in the middle ear and/or mastoid. "Exon sequencing of these genes in 17 cholesteatoma/blood test pairs revealed that somatic variants in MYC and NOTCH1 had the highest frequencies among the examined genes." (PMID 37968650, 2023). "According to our opinion the c-MYC expression level is a prognostic factor in cholesteatoma, indicating the clinical aggressiveness and the susceptibility of relapse." (PMID 24683550, 2014). "The aim of our study was to determine the expression level of the c-MYC protooncogene, a plausible causative factor of the hyperproliferation of the epithelium (matrix) in cholesteatoma." (PMID 24683550, 2014). "NOTCH1 and MYC mutations correlated significantly with bone destruction (p = 0.0148) but not with granulation tissue formation (p = 0.399) in attic cholesteatomas (n = 14)." (PMID 37968650, 2023). "Mutations in cholesteatomas, including NOTCH1 and MYC, were significantly correlated with bone destruction." (PMID 37968650, 2023). "The upregulation of the c-MYC gene suggests participation of the mucosa in the development of the cholesteatoma disease, which should be further investigated in future studies." (PMID 32915926, 2020). "Although not always significant, there is a clear trend for the upregulation of c-MYC in the mucosa from TC in patients with cholesteatoma." (PMID 32915926, 2020). "In cholesteatoma, the keratinising squamous epithelium is believed to possess hyperproliferative characteristics, illustrated by the upregulation of the c-MYC gene within the cholesteatoma matrix." (PMID 32915926, 2020). "In order to compare c-MYC gene expression 26 acquired cholesteatoma samples (15 children and 11 adults), 15 atheroma samples, and 5 normal skin samples were collected." (PMID 24683550, 2014). "We have found significantly elevated c-MYC gene expression in cholesteatoma compared to atheroma and to normal skin samples." (PMID 24683550, 2014). "Previous studies had shown aneuploidy of chromosome 8 and as a consequence copy number variation of c-MYC gene and the presence of elevated level c-MYC protein in cholesteatoma." (PMID 24683550, 2014). "In cholesteatoma samples, however, c-MYC expression level was significantly elevated (μ ± SD = 6.9 × 10−3 ± 1.08 × 10−3) compared to that in atheroma (P = 0.0001) and in control samples (P = 0.012)." (PMID 24683550, 2014). "Mean relative expression level of c-MYC in cholesteatoma samples of children was slightly higher than in the adults (μ ± SD = 9.1 × 10−3 ± 1.17 × 10−3 and 6.3 × 10−3 ± 1.0 × 10−3, resp)." (PMID 24683550, 2014). "This examination is in agreement with the increased c-MYC expression in childhood cholesteatomas found in our study." (PMID 24683550, 2014). "Ozturk and coworkers showed the aneuploidy of chromosome 8 and subsequent copy number variation of the c-MYC gene in cholesteatoma." (PMID 24683550, 2014). "Interestingly, recent studies using microarray analysis techniques have demonstrated that cholesteatomas express many tumor-related genes, including proto-oncogenes c-MYC and NOTCH1." (PMID 37968650, 2023). "Increased level of c-MYC protein was also detected by immunohistochemistry in cholesteatoma." (PMID 24683550, 2014). "Based on these results, one might conclude that the increased expression of the c-MYC in cholesteatoma is induced by inflammation." (PMID 24683550, 2014). "Based on the elevated c-MYC expression level, cholesteatoma is similar to a neoplastic malformation; however, further experiments are needed to clarify its role in the pathogenesis of cholesteatoma." (PMID 24683550, 2014).